TLR9 (toll like receptor 9)
Diseases named in the same sentence as TLR9 in open-access papers (continued):
Sharing a sentence is not in itself a finding about the gene and the disease.
schizophrenia (2 papers, 2016 to 2023). A major psychotic disorder characterized by abnormalities in the perception or expression of reality. "There is evidence that the cfDNA in patients with schizophrenia stimulated the expression of the TLR9 and STING genes while simultaneously blocking the expression of RIG-I and AIM2, which are involved in cfDNA sensing and activate the inflammatory response." (PMID 36834811, 2023).
sialadenitis (2 papers, 2022 to 2024). Sialadenitis is an infection of the salivary glands. "Hence, we can hypothesize that the accelerated sialadenitis and autoimmune phenotype in the TLR9-deficient MRL/lpr mice is due to the increased TLR7 signaling by B cells, however, this aspect was not addressed in the study." (PMID 36389822, 2022). "Since TLR7 and TLR9 are critical in SLE development some studies focused on determining whether TLR7 or TLR9 activation could contribute to sialadenitis in NOD mice." (PMID 36389822, 2022). "Moreover, administration of chloroquine, which inhibits the activation of endosomal nucleic acid-sensing TLRs, in NOD mice starting at 4 weeks of age, abolished the elevated expression of TLR1, TLR2, TLR3, TLR4 and TLR9 and reduced sialadenitis in 16 weeks old mice." (PMID 36389822, 2022). "Thus, depending on the experimental settings and type of activation TLR9 signaling might have a beneficial or detrimental effect on the development and/or progression of sialadenitis and salivation in NOD mice." (PMID 36389822, 2022).
sickle cell disease (2 papers, 2022 to 2023). Sickle cell anemias are chronic hemolytic diseases that may induce three types of acute accidents: severe anemia, severe bacterial infections, and ischemic vasoocclusive accidents (VOA) caused by sickle-shaped red blood cells obstructing small blood vessels and capillaries. "A Previous study has confirmed that cell-free mtDNA triggers NETs formation by the TLR9 pathway during lung transplantation and by the cGAS-STING pathway in sickle cell disease." (PMID 37794018, 2023).
silicosis (2 papers, 2019 to 2024). Silicosis is a respiratory disease caused by breathing in (inhaling) silica dust. "Another study showed that mitoDNA could activate neutrophils via TLR9 and cause severe inflammatory responses in the lung tissues of mice with silicosis." (PMID 38384409, 2024). "Such requirement was further observed in inflammatory models where DNA sensing via TLR9 contributes to disease, such as silicosis and drug-induced liver injury." (PMID 31836766, 2019). "Of note, to the best of our knowledge, we are the first group to demonstrate a correlation between the TLR9 and PI3Kγ pathways for the development of silicosis." (PMID 31836766, 2019). "Whilst a functional link is provided by the CpG models, we cannot unequivocally establish that TLR9 and PI3Kγ activation are dependent of each other in the more complex models of APAP injury or silicosis due to the limitations of the experimental approach." (PMID 31836766, 2019). "Here, we clearly demonstrate that, in the absence of TLR9, these animals were protected from silicosis since they showed less lung inflammation, reduced fibrosis and improved lung function." (PMID 31836766, 2019).
thymoma (2 papers, 2014 to 2017). A neoplasm arising from the epithelial cells of the thymus. "We also compared mRNA levels of TLR7 and TLR9, two endosomal-lysosomal receptors able to recognize bacterial or viral RNA and DNA and found significantly increased in EBV-positive hyperplastic MG thymuses, among normal thymuses, MG and non-MG thymomas." (PMID 29221139, 2017).
typhoid fever (2 papers, 2012 to 2019). A bacterial infectious disorder contracted by consumption of food or drink contaminated with Salmonella typhi. "The typhoid fever and BCG vaccines, which carry the same formula since their creation in 1911 and 1921, respectively, have DNA as adjuvant to activate TLR9." (PMID 30802247, 2019).
vaginal infection (2 papers, 2018 to 2023). "Toll-like receptor 3 (TLR3) and toll-like receptor 9 (TLR9)-mediated antiviral defense were not expressed during vaginal infection with herpes simplex virus 2 in IFN-λR1 knockout mouse." (PMID 36911685, 2023). "To clarify the role of TLR2 and TLR9 in inflamed tissues after mucosal HSV infection, we assessed the survival of WT, TLR2 KO, TLR9 KO, and TLR2/9 DKO mice following vaginal infection with different doses of the HSV-1 McKrae strain (1 × 106, 1 × 107, and 5 × 107 pfu/mouse)." (PMID 29760708, 2018).
venous thromboembolism (2 papers, 2017 to 2021). Occlusion of the lumen of a vein by a thrombus that has migrated from a distal site via the blood stream. "Recent gene knockout studies on mice have shown the role of toll-like receptor 9 (TLR9) in resolution of venous thromboembolism (VTE) through sterile inflammation." (PMID 28321710, 2017).
Acute hepatitis (1 paper, 2017). Acute hepatic injury resulting from inflammation typically accompanied by increased serum alanine transaminase activity. "Administration of the anti-TLR9 mAb protected mice from acute hepatitis caused by the TLR9 ligand and D-(+)-galactosamine, and these results demonstrate that the anti-TLR9 mAb is a promising tool to control TLR9-dependent inflammatory diseases." (PMID 28266597, 2017).
adult-onset Still disease (1 paper, 2022). A rare inflammatory multisystem disorder characterized clinically by fever of unknown origin, arthralgia or arthritis, hyperleucocytosis, and typical skin rash. "This study investigated the role of Toll-like receptor 1 (TLR1), TLR2, TLR4, TLR7, and TLR9 in patients with adult-onset Still’s disease (AOSD)." (PMID 35715478, 2022).
aneurysm (1 paper, 2024). Bulging or ballooning in an area of an artery secondary to arterial wall weakening. "However, based on our results it can be assumed that TLR4 and TLR9 respond not only to blood degradation products but also to increased ICP following aneurysm rupture and extravasation of blood into the subarachnoid space." (PMID 39839349, 2024).
autoimmune uveitis (1 paper, 2013). An autoimmune form of uveitis (disease). "Our previous studies showed that signaling of TLR2, TLR3, TLR4, and TLR9 is highly redundant in the adjuvant effect needed to induce experimental autoimmune uveitis (EAU)." (PMID 23207548, 2013).
bacterial vaginosis (1 paper, 2015). Infection caused by bacterial overgrowth in the vagina. "This study has produced an overview of potential TLR9 activation through inflammation stimulating or inhibiting CpG motifs related to a variety of bacterial STDs, bacteria linked to bacterial vaginosis, and commensal bacteria found in the genital tract." (PMID 26179610, 2015).
bovine tuberculosis (1 paper, 2014). "Indeed, the TT genotype at TLR9 2340 C > T locus resulted significantly associated with susceptibility to bovine tuberculosis (P = 0.030, OR = 3.31, 95% CI = 1.05-10.40)." (PMID 25496717, 2014).
breast adenocarcinoma (1 paper, 2019). "Treatment of DA3 breast adenocarcinoma tumors with DaRT in combination with the TLR9 agonist CpG retards local tumor growth, relative to DaRT alone or to CpG alone." (PMID 31637474, 2019).
breast tumours (1 paper, 2011). "However, a remarkable percentage (57.5%) of recurrent breast tumours was shown to express TLR9 by fibroblast-like cells and these tumours have reported to have low probability of metastasis." (PMID 21929816, 2011).
Cachexia (1 paper, 2015). Severe weight loss, wasting of muscle, loss of appetite, and general debility related to a chronic disease. "More importantly, neither TLR7/9 blockade nor genetic deletion of TLR9 improved overall mortality or the metabolic changes of pancreatic cachexia in our validated mouse model." (PMID 26172047, 2015).
campylobacteriosis (1 paper, 2011). Infections with bacteria of the genus campylobacter. "The C. jejuni strains used for analysis of campylobacteriosis in mice presented here were neither studied for TLR9 activation in human nor murine cell lines before." (PMID 21698299, 2011). "However, this does not rule out a role for TLR9 in human campylobacteriosis." (PMID 21698299, 2011).
cerebral edema (1 paper, 2019). "The amelioration of brain edema and cytokine production by ODN2088 supports exploration of TLR9 antagonism as a therapeutic modality in early ALF to prevent the development of brain edema and intracranial hypertension." (PMID 31401214, 2019). "Using an acute hyperammonemic mouse model, we demonstrated that ammonia-induced brain edema and immune dysfunction, as measured by increased brain water (BW) content and intracellular cytokine production of macrophages and T cells are mediated through TLR9." (PMID 31401214, 2019). "We hypothesized that ammonia-induced brain edema and immune dysfunction are mediated by TLR9." (PMID 31401214, 2019). "Therefore, we could not utilize an acetaminophen-induced model of ALF to assess TLR9-mediated cerebral edema in this study and thus chose to examine this in a model of ammonia-induced cerebral edema." (PMID 31401214, 2019).
Cervical Dysplasia (1 paper, 2025). "The primary goal of this study was to investigate the association between SNPs in TLR-4 and TLR-9 with cervical dysplasia severity and HPV infection." (PMID 41374999, 2025). "Our study provides novel evidence that specific SNPs in TLR4 and TLR9 are associated with an increased risk of cervical dysplasia and HR-HPV infection in our patients." (PMID 41374999, 2025). "This study evaluated the presence of single-nucleotide polymorphisms (SNPs) in Toll-like receptors (TLR4 and TLR9) among women with cervical dysplasia and HPV infection, as potential immune-related susceptibility factors." (PMID 41374999, 2025). "This study provides the first evidence of an association between specific SNPs in TLR4 and TLR9 and the severity of cervical dysplasia and HR-HPV infection in a cohort of Hispanic women from Puerto Rico." (PMID 41374999, 2025). "Our main objective was to explore the correlation of four SNPs of TLR 4 and three SNPs of TLR-9 with the presence of cervical dysplasia and HPV infection in the cervicovaginal lavages of women attending a gynecology clinic." (PMID 41374999, 2025).
Chronic colitis (1 paper, 2023). A chronic inflammatory disease of the large intestine (colon, cecum and rectum). "Suppression of TLR9 signaling by adenoviral oligodeoxynucleotides has been shown to suppress intestinal inflammation in several mouse models of chronic colitis." (PMID 37519301, 2023).
chronic gastritis (1 paper, 2011). Inflammation of the stomach that is chronic in nature. "TLR5 and TLR9 have also been identified in non-inflamed gastric epithelium and in H. pylori-associated chronic gastritis." (PMID 21647408, 2011). "The localization of TLR5 and TLR9 was found to be exclusively basolateral in H. pylori-associated chronic gastritis, suggesting that these two TLRs may not be essential for H. pylori recognition." (PMID 21647408, 2011).
corneal disease (1 paper, 2022). "In contrast, in the mTLR4KO and their WT littermates, GLY significantly reduced corneal disease, TLR4, TLR9, HMGB1, and RAGE corneal mRNA expression after infection." (PMID 36422579, 2022).
coronavirus infectious disease (1 paper, 2024). "TLR9 activation has also been reported to be induced by severe acute respiratory syndrome coronavirus 2 (coronavirus infectious disease, emerged in 2019) infection via mtDNA." (PMID 38354781, 2024).
cutaneous squamous cell carcinoma (1 paper, 2020). "Most recently, SNAs targeting toll-like receptor 9 are being used in Phase 2 human trials via intratumoral injection to induce immune responses in Merkel cell and cutaneous squamous cell carcinoma." (PMID 33147737, 2020).
dementia (1 paper, 2024). Loss of intellectual abilities interfering with an individual's social and occupational functions. "Further research into the potential role of TLR9 signaling in AD, including the identification of additional families with early-onset dementia harboring pathogenic TLR9 mutations, is now needed." (PMID 39421070, 2024).
diabetic neuropathy (1 paper, 2025). A chronic, pathological complication associated with diabetes mellitus, where nerve damages are incurred due to diabetic microvascular injury involving small blood vessels that supply these nerves, resulting in peripheral and/or autonomic nerve dysfunction. "Severe diabetic neuropathy was reduced by TLR9 inhibition, confirming the therapeutic benefit of TLR9 targeting in the management of certain pain conditions." (PMID 40149566, 2025).
diastolic heart failure (1 paper, 2015). Heart failure caused by abnormal myocardial relaxation during diastole leading to defective cardiac filling. "Here we investigated the impact of systemic inflammation, caused by sustained Toll-like receptor 9 activation, on established diastolic heart failure." (PMID 26461521, 2015). "Sustained activation of Toll-like receptor 9 causes cardiac and systemic inflammation, and deterioration of SERCA2a depletion-mediated diastolic heart failure." (PMID 26461521, 2015).
Dysmenorrhea (1 paper, 2017). Pain during menstruation that interferes with daily activities. "After statistical analysis confirmed that: The gene expression of TLRS (TLRS = TLR1 + TLR2 + TLR3 + TLR4 + TLR5 + TLR6 + TLR7 + TLR8 + TLR9) in severe and moderate dysmenorrhea group was significantly higher than that in minimal dysmenorrhea group in EU and EC (P < 0.05 or P < 0.01)." (PMID 28779087, 2017).
edema (1 paper, 2019). An abnormal accumulation of fluid beneath the skin, or in one or more cavities of the body. "In summary, this study demonstrates that the development of ammonia-induced brain edema requires macrophage and T cell expression of TLR9, which may be stimulated by DNA release." (PMID 31401214, 2019).
empyema (1 paper, 2017). An accumulation of pus in a body cavity, usually the pleural space. "HO-1 deficiency diminished the TLR expression, particularly TLR9 indicating that HO-1 regulates TLRs expression in PMCs thus may contribute to pleural innate immune functions during MRSA empyema." (PMID 28052108, 2017). "Our findings suggest that HO-1 by modulating TLR9 expression in PMCs promotes pleural innate immunity in MRSA empyema." (PMID 28052108, 2017). "Here we seek to determine the role of HO-1 on TLR9 mediated pleural mesothelial innate immune function in MRSA empyema." (PMID 28052108, 2017).
enterocolitis (1 paper, 2024). An inflammatory process affecting the small intestine and colon. "In literature it was shown that different gram-positive lactobacilli, e.g. Lactobacillus rhamnosus HN001 are able to activate TLR9 and improve enterocolitis in neonatal mice or preterm piglets." (PMID 39567370, 2024).
epidermodysplasia verruciformis (1 paper, 2025). A rare inherited genodermatosis characterized by chronic infection with human papillomavirus (HPV) leading to polymorphous cutaneous lesions and high risk of developing non melanoma skin cancer. "This study demonstrates significantly reduced TLR3 and TLR9 expression in both normal skin and flat warts of Epidermodysplasia Verruciformis (EV) patients compared to immunocompetent individuals (NEV)." (PMID 41211638, 2025).
gastric adenocarcinoma (1 paper, 2013). "Furthermore, a similar trend in TLR9 mRNA expression was also detected in the Caco-2 and AGS human colorectal and gastric adenocarcinoma cell lines, respectively." (PMID 24273604, 2013).
gestational diabetes (1 paper, 2022). Carbohydrate intolerance first diagnosed during pregnancy. "TC and CC genotypes in TLR9 rs187084 were significantly less common in women with PTL, compared to the controls, after adjusting for bleeding and gestational diabetes." (PMID 35877427, 2022).
Giardia infection (1 paper, 2021). "To explore the role of TLR9 in Giardia infection, we first assessed TLR9 gene expression levels at different time points (0, 2, 4, 6, 8, and 12 h) using reverse transcriptase (RT)–quantitative PCR (qPCR)." (PMID 34336841, 2021). "Several studies have demonstrated that innate immunity-associated Toll-like receptors (TLRs) are critical for the elimination of G. duodenalis; however, whether TLR9 has a role in innate immune responses against Giardia infection remains unknown." (PMID 34336841, 2021). "Notably, our study was performed on mouse macrophages infected with G. duodenalis, whereas Giardia muris might be a better option for establishing a model of Giardia infection in mice; moreover, Giardia-induced activation of TLRs, including TLR9, may differ among Giardia species." (PMID 34336841, 2021).
glaucoma (1 paper, 2023). Increased pressure in the eyeball due to obstruction of the outflow of aqueous humor. "NFKB1, TLR9, and HDAC4 were predicted to be upregulated in glaucoma and their mRNA level increased according to the RT-qPCR data, meanwhile, IL18 was predicted to be downregulated in glaucoma and its mRNA level was also increased according to RT-qPCR." (PMID 37605653, 2023). "This study identified IL18, TLR9, NFKB1, HDAC4, FKBP2, and KITLG as hub genes in glaucoma that are gut microbiota-related as well as showed that the regulation of immune response by gut microbiota is associated with glaucoma." (PMID 37605653, 2023).
graft versus host disease (1 paper, 2021). An immune system disorder that occurs after allogeneic hematopoietic stem cell transplant and is a reaction of donor immune cells against host tissues. "The TLR9 rs352139 and rs352140 SNPs had a significant impact on the risk of acute graft-versus-host disease and early CMV infection in allogeneic hematopoietic recipients." (PMID 34572011, 2021). "Clinical evidence has also demonstrated that the donor homozygous recessive genotype of the TLR9 1635A/G SNP was associated with a higher incidence of CMV reactivation and yielded a protective effect against acute graft versus host disease in allo-HSCT recipients." (PMID 34572011, 2021).
gynecologic cancer (1 paper, 2022). "However, several studies have reported that TLR9 is associated with the development of cancers, especially gynecologic cancer." (PMID 35937402, 2022).
hairy cell leukemia (1 paper, 2022). Hairy cell leukemia (HCL) is a rare type of leukemia in which abnormal B-lymphocytes are present in the bone marrow, spleen and peripheral blood. "However, a recent study involving ex vivo peripheral blood mononuclear cells (PBMCs) from patients with hairy cell leukemia (HCL) revealed that the cytotoxic effects of venetoclax against HCL cells was significantly reduced following TLR9 stimulation with CpG." (PMID 36341439, 2022).
hearing (1 paper, 2012). "Carriage of one or more mutant alleles in combined carriership of TLR4+896 and TLR9 -1237 increases the risk for hearing loss in BM patients (p = 0.0006, OR 4.1, 95% CI 1.8–9.4, in MM patients: p = 0.02, OR 4.3 95% CI 1.3–14.2, in PM patients: p = 0.003, OR 6.0, 95% CI 1.7–21.3)." (PMID 22662111, 2012).
hearing loss (1 paper, 2012). "Carriage of one or both mutant alleles in TLR4+896 and TLR9 -1237 increases the risk for hearing loss (p = 0.0006, OR 4.1 in BM)." (PMID 22662111, 2012). "This may either be due to an increased incidence of hearing loss in the PM group (21%) compared to 4% in the MM group, or to differences in pathogenesis and recognition of these two different pathogens by TLR9." (PMID 22662111, 2012).